CRP (C-reactive protein)
Diseases named in the same sentence as CRP in open-access papers (continued):
Sharing a sentence is not in itself a finding about the gene and the disease.
pneumonia (continued). "The clinical parameters elevated body temperature, heart rate, and respiratory rate, increased lactate dehydrogenase (LDH), aspartate aminotransferase (AST), and C-reactive protein (CRP) levels as well as lower serum albumin level and lymphocyte count were linked with a pneumonia." (PMID 34068311, 2021). "However, a recent Danish study found that even a slightly elevated CRP (>11 mg/L) was positively associated with patients being diagnosed with pneumonia and consequently treated with antibiotics." (PMID 34205866, 2021). "It is well known that CRP and oxygenation are associated with the severity of pneumonia." (PMID 33147270, 2020). "Severe disease was strongly associated with fever, cough, dyspnea, pneumonia, any computed tomography findings, any ground glass opacity, lymphocytopenia, elevated C-reactive protein, elevated alanine aminotransferase, elevated aspartate aminotransferase, older age and male sex." (PMID 32941548, 2020). "Moreover, meta-analyses showed that when CRP is added to the assessment of pneumonia in primary care, the diagnostic discrimination improved but in patients with intermediate risk at the decision making the challenge remains." (PMID 33399009, 2020). "The age-adjusted univariate logistic regression analysis showed that age, male sex, baseline ADL impairment, a comorbidity score of 2 or more, fever, infiltration at initial chest X-ray, and CRP at admission were associated with severe pneumonia and death of elderly patients with COVID-19 infection." (PMID 33291617, 2020). "Associations between reported symptoms, findings and CRP values and being diagnosed with pneumonia." (PMID 31650886, 2020). "This study aimed to describe differences in reported symptoms, findings and management of patients diagnosed with either acute bronchitis or pneumonia in general practice, and to explore possible associations between the symptoms, findings, and CRP level and being diagnosed with pneumonia." (PMID 31650886, 2020). "Moreover, it also seems that CRP test cannot be used as a stand-alone diagnostic test for pneumonia." (PMID 31110214, 2019). "According to our data, among the elderly, a respiratory disease that elevates CRP to over 100 mg/l could be linked to death on the count of that in such cases pneumonia is probable." (PMID 30991957, 2019). "Our result revealed that the diagnostic role of CRP > 20 mg/l has value in ruling in pneumonia." (PMID 31110214, 2019). "We enhanced an existing hospital-based pneumonia surveillance system by incorporating additional study components (nasopharyngeal swabbing using standard methods, C-reactive protein, risk factor assessment) and strengthening clinical practices, such as radiology as well as monitoring and training." (PMID 30898094, 2019). "C-reactive protein is also consistently associated with the presence of pneumonia." (PMID 30991716, 2019). "However, this study did find that a CRP over 80 mg/l and a WBC over 15 × 109/L were linked to pneumonia and a CRP over 100 mg/l to elevated mortality during hospital stay." (PMID 30991957, 2019). "Referral mechanisms therefore mitigated the remaining risks for the nurses when patients had low CRP but suspected pneumonia, which underlined the role of the health policy environment as a further determinant of the risks that HCWs perceived when not prescribing an antibiotic." (PMID 30736818, 2019). "Considering the fact that, in 8 of the 20 patients who died within 30 days of PEG, death was associated with infection, pneumonia, or peritonitis, elevated CRP levels may be significantly associated with post-PEG prognosis." (PMID 29954339, 2018). "This large study of hospitalized severe and very severe pneumonia from 7 countries in Africa and Asia showed that elevated CRP was positively associated with confirmed bacterial pneumonia and negatively associated with RSV pneumonia as defined for this analysis." (PMID 28575375, 2017).
pneumonia (continued). "Patients starting due to pulmonary stasis and dyspnea had very high values of CRP, suggesting that complicating pneumonia may have been a partial cause of their distress." (PMID 29261657, 2017). "During the aging process, there may be several elements biasing the association between pneumonia and elevation in serum of CRP or procalcitonin." (PMID 26772604, 2016). "CRP is a well-established biomarker in many clinical settings, but has been traditionally considered not enough specific to be a useful guide in the diagnostic process of pneumonia." (PMID 26772604, 2016). "Moreover, chest radiography images, WBC count, and C-reactive protein level are recommended in elderly patients who are at high risk of procedure-related pneumonia." (PMID 26438198, 2015). "Age, NIHSS score, IL-6, CRP and dysphagia were significantly associated with pneumonia." (PMID 23935729, 2013). "IL-6 and CRP levels were significantly associated with pneumonia." (PMID 23935729, 2013). "However, recent systematic reviews have questioned the diagnostic accuracy of CRP for serious bacterial infections in febrile children, pneumonia, and neonatal sepsis." (PMID 22943554, 2012). "In our study, limited by the small number of patients, CRP levels of >60 mg/l were present in 20 of all 32 (= 63%) children with bacterial pneumonia and had a high diagnostic accuracy of 93.6% for diagnosis of pneumonia." (PMID 20302606, 2010). "Additionally, how PCT and CRP levels are modified by other prevalent causes of pneumonia in an area with high HIV-prevalence, such as PCP, should be assessed in future studies." (PMID 20976241, 2010). "Although there is some evidence suggesting that the serum C-reactive protein (CRP) concentration is higher in pneumonias caused by Streptococcus pneumoniae or Legionella pneumophila than in those caused by other agents, the relation of CRP to the aetiology of pneumonia is controversial." (PMID 16433910, 2006). "Likewise, among patients hospitalized with a primary diagnosis of pneumonia, a one-day increment in CRP greater than 50 mg/L was associated with a greater severity of illness or bacteremia, while survival has been linked to a 50% reduction in CRP." (PMID 41523477, 2025). "Furthermore, we evaluated whether routinely-measured serum markers of inflammation such as C-reactive protein may be associated with future risk of pneumonia." (PMID 38105941, 2023). "In a multivariate logistic regression, the age (OR = 1.034, 95% CI: 1.012–1.057, p = 0.003), CRP (OR = 1.051, 95% CI: 1.025–1.077, p = 0.000) and eosinophil count (OR = 0.026, 95% CI: 0.001–0.931, p = 0.046) were significantly associated with the development of pneumonia." (PMID 37570378, 2023). "Moreover, low serum albumin level was associated with pneumonia, dyspnea, over 13-night long stay at ward, death at ward and serum CRP value over 100 mg/L in multivariable logistic regression analysis (P = 0.01, P = 0.02, P = 0.006, P < 0.0001 and P < 0.0001, respectively)." (PMID 35189828, 2022). "It was concluded through analysis that the use of hormones (χ2 = 14.203, P = 0.000), neutropenia or agranulocytosis (χ2 = 17.938, P = 0.000), Hb < 90 g/L (χ2 = 9.947, P = 0.002), and CRP > 15 mg/L (χ2 = 10.493, P = 0.001) were independent influencing factors that may cause severe pneumonia." (PMID 35601429, 2022). "However, one can speculate if the CRP test is used too extensively in Danish general practice, as even a very low cut-off (>11 mg/L) was associated with being diagnosed with pneumonia." (PMID 31650886, 2020). "Subject S10, who previously had pneumonia, suffered the longest hospitalization period (37 days) and had an extremely high level of serum CRP (121.2 mg/l) during hospitalization, which may be caused by bilateral pulmonary effusion and necrotizing lung consolidation." (PMID 29789582, 2018). "The CRP test may be most useful in patients with an intermediate risk of pneumonia." (PMID 24886066, 2014).
pneumonia (continued). "In conclusion, the data indicate that cellular analysis of BAL fluid, alone or in combination with serum procalcitonin and C-reactive protein concentrations, may rapidly provide valuable diagnostic information for the early differential diagnosis of pneumonia in critically ill adult patients." (PMID 24824328, 2014). "However, other postoperative infectious complications such as urinary tract infections or pneumonia may also cause high CRP values and need to be recognized." (PMID 21657968, 2011). "Our recent observation that many children with viral-associated pneumonia have a bacterial super-infection, however, suggests that a high level of CRP and procalcitonin may be associated with unrecognised bacterial co-infection in a child with an established viral aetiology for pneumonia." (PMID 15736995, 2005). "(2024) reported that the white blood cell count (WBC)/mean platelet volume (MPV) and C-reactive protein (CRP)/MPV ratios were significantly elevated in patients with pneumonia requiring hospitalization." (PMID 41602115, 2026). "The model's cutoffs for PCT (>2 ng/mL) and CRP (>40 mg/L) align with existing pediatric pneumonia predictive scores (e.g., PRIEST score) but offer improved discriminative power by integrating multi-dimensional indicators and ML-driven interactions." (PMID 41684921, 2026). "Logistic regression identified C-reactive protein and albumin as independent predictors of pneumonia." (PMID 41641131, 2026). "Serum levels of procalcitonin, creatinine, and C-reactive protein were elevated in pneumonia patients, while albumin levels were decreased." (PMID 41641131, 2026). "After including CRP >100 mg/L, pneumonia diagnosis, and ICU admission as covariates, gentamicin use was no longer significantly associated with prolonged hospitalization (p = 0.41)." (PMID 41304809, 2025). "Patients with RSV infections presented with severe symptoms, including dyspnea, elevated ESRs and CRP levels, and frequent pneumonia observed on chest X-rays." (PMID 40559551, 2025). "Severe pneumonia was associated with higher IL-10 and PCT levels (both serum and saliva), younger age, elevated heart rate, and higher CRP." (PMID 41018059, 2025). "The Emergency Department of Wan Fang Hospital found that COPD patients with pneumonia had significantly higher CRP levels than those with AECOPD (median: 6.7, IQR: 23.6–2.4) (p = 0.001)." (PMID 39872908, 2025). "Among them, the prediction model with age, severe pneumonia, bilateral pneumonia, ground-glass attenuation, consolidation, atelectasis, CRP, and LDH as the main variables achieved an AUC of 0.866 (95%CI: 0.831-0.901) for distinguishing adenovirus from MP." (PMID 40171163, 2025). "Children with severe pneumonia exhibited significantly higher CRP levels (median: 46.8 mg/L, IQR: 12.5–60.8) compared to those with non-severe disease (median: 27.0 mg/L, IQR: 2.3–51.9; p = 0.034)." (PMID 41018059, 2025). "Severe pneumonia caused by bacteria usually has a significant increase in WBC, CRP and PCT in the early stage of the disease." (PMID 40171163, 2025). "Female Sex, presence of bipedal oedema, WHZ, HAZ, MUAC, CRP, presumptive TB and HIV status of the mother were factors associated with presence of pneumonia at admission on bivariate analysis." (PMID 41026768, 2025). "In KD patients with pneumonia-like changes, there were significant elevations in inflammatory markers including the C-reactive protein (CRP) (P = 0.011), white blood cell (WBC) (P = 0.027), NT-proBNP (P = 0.007), and D-dimer (D-D) (P = 0.002) levels." (PMID 39981208, 2025). "Serum albumin and C-reactive protein (CRP) are widely recognized biomarkers for diagnosing and monitoring systemic inflammatory conditions, including pneumonia." (PMID 40248251, 2025). "IL-6 levels were positively correlated with age, C-reactive protein (CRP), and pneumonia severity index (PSI) scores." (PMID 40572766, 2025).
pneumonia (continued). "On the 12th day of symptoms, he returned to the ED and was diagnosed with pneumonia, based on mild infiltration observed in the lower right lung lobe on a chest X-ray and an elevated C-reactive protein (CRP) level of 12 mg/dL." (PMID 41573439, 2025). "A case report introduced the impact of intravenous lidocaine on a patient with severe pneumonia, observing a significant decrease in D-dimer and CRP levels, indicating a good response to lidocaine treatment without adverse events." (PMID 40338919, 2025). "The identified risk factors for infection-attributable deaths included older age, malignancy, liver cirrhosis, corticosteroid use, septic shock, pneumonia, persistent bacteremia, failure to remove an eradicable focus, and elevated CRP." (PMID 39776932, 2025). "Correlations between serum zinc and clinical-laboratory parameters further details the strength and direction of these associations, indicating that lower zinc levels correlate with elevated CRP, higher granulocyte count, and more severe pneumonia." (PMID 41487803, 2025). "Shred sign (odds ratio (OR)=8.45) and CRP >20 mg/L (OR=3.50) emerged as strong independent predictors of pneumonia." (PMID 41049999, 2025). "Previous research has highlighted the significant role of serum CRP levels in the progression and prognosis of pneumonia, which aligns with our findings that CRP can provide valuable predictive insights into the severity of neonatal pneumonia." (PMID 40529154, 2025). "From day 9, after the diagnosis of pneumonia and in view of persistent hyperleukocytosis and an increase of C-reactive protein (CRP), piperacillin with clavulanic acid was started." (PMID 40519552, 2025). "The granules significantly improved the chest CT absorption rate, pneumonia severity, and CRP and LC levels (p < 0.05)." (PMID 40103592, 2025). "Positive signs of proGRP coefficients and CRP coefficients from MNLR models increase the likelihood of pneumonia/COPD and NET over ADC/SQCC." (PMID 39703761, 2025). "The high ranking of “Radiological findings” and “CRP” is consistent with literature that identifies them as strong indicators of the parenchymal inflammation characteristic of pneumonia." (PMID 40941745, 2025). "Median CRP levels at baseline were moderately elevated, approximately seven times the normal value, consistent with the previous studies linking increased CRP levels to pneumonia severity." (PMID 40284719, 2025). "Auxiliary examinations revealed elevated serum C-reactive protein levels and lobar pneumonia changes on chest CT." (PMID 40901522, 2025). "During the patient’s hospitalization this time, Hypersensitive C-reactive protein was found to be elevated, and imaging suggested pneumonia." (PMID 41357223, 2025). "They collected saliva and serum at the initial admission and during a follow-up from pediatric patients with pneumonia and observed that the salivary CRP level was much higher in pediatric patients with pneumonia than in healthy children." (PMID 40871545, 2025). "Through LASSO and multivariate logistic regression analysis, we identified respiration rate, weight, CRP, NEU, HGB, UA, and BUN as the main risk factors for neonatal severe pneumonia." (PMID 40529154, 2025). "Our patient initially presented with fever, dyspnea, elevated inflammatory markers (CRP, ferritin) and increased lung infiltrates, raising concerns for pneumonitis or pneumonia." (PMID 40391237, 2025). "Subgroup analysis revealed that low ferritin levels were especially protective against AKI and pneumonia in patients with elevated CRP (>10 mg/L), postmenopausal women, and those aged 18–64." (PMID 41445831, 2025). "As described in the features section, each disease class was mapped to literature-supported protein and gene expression profiles (MMP-9 and TGF-β for bronchiectasis, CRP and IL-6 for pneumonia, and IL-5 and YKL-40 for asthma)." (PMID 40806268, 2025).
pneumonia (continued). "C-reactive protein (CRP) levels, ranged 35 mg/L to 146 mg/L, and the median WBC count were significantly increased in children with HMPV-associated pneumonia than the normal level." (PMID 40346698, 2025). "CRP is also an acute-phase protein and its levels increase sharply during acute bacterial infections such as pneumonia." (PMID 41181583, 2025). "Significantly elevated C-reactive protein (CRP) levels were observed in all patients, serving as a criterion for pneumonia diagnosis." (PMID 40566535, 2025). "Certain inflammatory biomarkers, including leukocyte count, procalcitonin (PCT), and C-reactive protein (CRP), have also been utilized to evaluate the prognosis of pneumonia." (PMID 41158450, 2025). "Within the COVID‐19 group, the pneumonia subgroup had lower T‐cell counts but higher levels of inflammatory factors, including C‐reactive protein (CRP) and interleukin‐6 (IL‐6)." (PMID 41146434, 2025). "The median CRP level in the group with pneumonia-like changes was 86.6 mg/L, which surpassed 75.2 mg/L reported in the cohort with non-pneumonia-like changes." (PMID 39981208, 2025). "In contrast, some studies showed a lower accuracy of procalcitonin in diagnosing pneumonia, compared to CRP and interleukin 6, and the added benefit of PCT in the NICU was viewed as minimal." (PMID 40257674, 2025). "Patients with pneumonia were statistically older and had higher levels of inflammatory markers (CRP, IL-6, and D-dimer)." (PMID 40969806, 2025). "Pneumonia was defined by new radiographic infiltrates plus clinical and laboratory findings (fever, purulent sputum, elevated CRP/PCT)." (PMID 40804831, 2025). "The majority of pediatric patients fulfill WHO pneumonia criteria, which were supported by a chest radiograph (63.8%), peripheral blood test (33.6%), and C-reactive protein (27.4%) analysis." (PMID 38996808, 2024). "Our results showed that with an increase in the extent of pneumonia, a CRP increases severalfold as well." (PMID 39064460, 2024). "In case of pneumonia (including severe pneumonia) Legionella UAT seems to be useless when CRP is under 130 mg/L in immunocompetent patients with a NPV at 100%." (PMID 38530466, 2024). "It is important to highlight that the present study excluded patients with active inflammatory diseases and CRP values exceeding 10 mg/L, which differs from the other study where 21.9% of patients had pneumonia." (PMID 39262165, 2024). "It has been noted that patients with measles complicated by pneumonia have prolonged elevated serum CRP values and that a second peak in CRP elevation can occur in patients with measles encephalitis." (PMID 39064460, 2024). "Our findings revealed that patients aged 6–16 and over 65 showed the highest incidence of complications such as pneumonia (100% and 88%, respectively), and the mean CRP levels were increased in these two age groups (56% and 78%)." (PMID 39457522, 2024). "High-sensitivity C-reactive protein (CRP) levels were elevated in only one case of severe pneumonia." (PMID 38464898, 2024). "In case of pneumonia, some biological findings are suggestive for Legionnaire’s disease (LD) including C-reactive protein (CRP)." (PMID 38530466, 2024). "It was also found during the 8-week period that there were high incidences of inflammation-related adverse events in both the pneumonia and non-pneumonia groups (fever 89.8% vs. 19.6, CRP elevation 73.5% vs. 9.1%, respectively)." (PMID 39768896, 2024). "It was estimated that CRP mediated 32.59% (95% CI: 17.90%, 47.27%) of the effect of BMI on pneumonia, which was higher than the proportion mediated by IL-6 (7.96% [95% CI: 1.79%, 14.14%]) and FEV1 (4.04% [95% CI: 0.34%, 7.74%])." (PMID 39337223, 2024). "Further studies are required to assess the optimal timing of CRP measurements for predicting pneumonia development in patients with acute aspiration bronchitis." (PMID 38525743, 2024).